MIR105-2 (microRNA 105-2)
Synonyms: hsa-mir-105-2; MIRN105-2; mir-105-2
Gene: MicroRNA gene on chromosome X (152,394,412 to 152,394,492, reverse strand). Ensembl gene ENSG00000207818.
Gene Ontology:
Biological process: miRNA-mediated post-transcriptional gene silencing
Cellular component: RISC complex
Homologues: Orthologues: chimpanzee ptr-mir-105 (100% identical), macaque mml-mir-105-2 (100% identical), rabbit MIR105-2 (100% identical), pig ssc-mir-105-2 (99% identical), dog MIR105B (93% identical), mouse Mir105 (83% identical). Paralogues in human: MIR105-1 (98% identical).